OLIG2 (oligodendrocyte transcription factor 2)
Diseases named in the same sentence as OLIG2 in open-access papers (continued):
Sharing a sentence is not in itself a finding about the gene and the disease.
glioblastoma (continued). "Different expression levels of Olig2, Nogo-A, Nestin and AQP4 have no independent prognostic impact in IDH-wildtype glioblastoma and show no distribution differences regarding age, clinical status and MGMT-promoter methylation status." (PMID 32160197, 2020). "In contrast, our data support findings from a recent study that suggest widespread co-expression of SOX2, OLIG2 and ZEB1 in glioblastoma, irrespective of key driver alterations." (PMID 28945795, 2017). "The traditional glioblastoma prognostic markers GFAP, S100, OLIG2, MAP2 and SYN were also analyzed and found to be indistinguishable among the intracranial glioblastoma xenografts." (PMID 25955030, 2015). "However, MGH57 (grade IV glioblastoma) revealed a relatively small subpopulation of malignant cells that do not express OLIG1, OLIG2, DLL1, CCND1, and IGFBPL1, but express ALDOC and ATP1A2." (PMID 33607293, 2021).
oligodendroglioma (35 papers, 2009 to 2025). A well-differentiated (WHO grade II), diffusely infiltrating neuroglial tumor, typically located in the cerebral hemispheres. "In this case, the patient had received the clinical diagnosis of neurofibromatosis type I. Case #17 showed an oligodendroglioma-like morphology (see later), diffuse OLIG2 nuclear positivity, but only focal expression of GFAP." (PMID 37891325, 2023). "Despite cell lineage studies, it is unclear why Olig2 is enhanced in oligodendrogliomas and astrocytomas." (PMID 37274223, 2023). "Diffuse staining patterns of Olig2 were observed and similar to oligodendrogliomas, Olig immunoreactivity was found localized to the nuclei." (PMID 37274223, 2023). "DLGNT diagnosis was made for oligodendroglioma-like tumours with Olig2 and neuronal immunoreactivity and a MAPK alteration associated with chromosome arm 1p deletion." (PMID 36264505, 2022). "Based on theabove features, all 6 oligodendrogliomas were classified as high grade.Intranuclear immunolabeling for OLIG2 in 70% to 100% of the neoplastic cells wasobserved in 4/5 cases." (PMID 35638647, 2022). "Except for the expression of CD34, GAFP positivity is usually seen in PLNTY and Olig-2, which indicates the neuroepithelial origin of the tumor and the oligodendroglioma-like components within the tumor." (PMID 35372027, 2022). "The classic pathologic features include low- to moderate-density cellular lesions with OLIG2 expression and evidence of ‘oligodendroglioma-like’ appearance." (PMID 34493325, 2021). "The human OLIG1 and OLIG2 express stronglyin oligodendroglioma with contrasting low expression in theastrocytoma." (PMID 31312081, 2019). "Oligodendrogliomas show highly positive results of Olig2 immunohistochemistry in contrast to liponeurocytomas." (PMID 29908563, 2018). "OLIG2 was reported high expressed in oligodendrogliomas and diffuse cerebellar gliomas." (PMID 37001387, 2023). "Specifically, anaplastic oligodendrogliomas displayed intense nuclear Olig2 expression." (PMID 37274223, 2023). "Interestingly, these Type B cells, along with some Type C (transit-amplifying) cells, also express Olig2, indicating possible cells of origin for astrocytomas and oligodendrogliomas." (PMID 37274223, 2023). "Several earlier studies have observed marked Olig2 expression in oligodendrogliomas." (PMID 37274223, 2023). "The pathological aspects of GNTs remain unclear however, case reports have found Olig2 commonly expressed in these tumors and thus lean more toward oligodendrogliomas." (PMID 37274223, 2023). "Oligodendrogliomas can show similar pathological findings demonstrating neuronal differentiation with glial and neuronal characteristics; however, oligodendrogliomas show highly positive results of Olig2 immunohistochemistry in contrast to liponeurocytomas." (PMID 33964714, 2021). "The presence of Olig2-positive cells might suggest the resemblance to GBMs with oligodendroglioma component, which represent approximately 20% of primary GBMs41." (PMID 29654229, 2018). "Olig2 has been identified as a transcription factor that regulates oligodendroglial development and has been reported to be useful in determining the diagnosis of oligodendroglioma." (PMID 24179531, 2013). "Both Olig2 and GFAP can be expressed in astrocytomas and oligodendrogliomas, whereas vimentin is more strongly expressed in astrocytomas." (PMID 40362055, 2025). "Astrocytomas and oligodendrogliomas were characterized by their typical histological features and, when required, further classified based on immunoreactivity against GFAP and Olig2 on >50% of neoplastic cells, respectively." (PMID 39061577, 2024). "With findings of cells exhibiting oligodendroglioma-like appearance, strong OLIG2 and synaptophysin expression, and absence of widespread GFAP expression, the diagnosis was revised to DGONC." (PMID 40475045, 2025).
oligodendroglioma (continued). "As our case demonstrated cells exhibiting oligodendroglioma-like appearance, strong OLIG2 and synaptophysin expression, and absence of widespread GFAP expression, the diagnosis of DGONC was assigned based on these morphological features." (PMID 40475045, 2025). "Expression of Olig2 is seen in all oligodendrogliomas, whereas none or little expression of this transcription factor in central neurocytoma has been found." (PMID 24877104, 2014). "Oligodendrogliomas exhibit a proneural genetic signature and the OG cells expressed NG2 and PDGFRα; however, they did not express the proneural markers Sox2, CD133, or Olig2 and only expressed low levels of Notch1 and nestin." (PMID 24278309, 2013).
astrocytoma (23 papers, 2005 to 2025). "Conversely, Olig2-CKO tumors are highly diffuse “astrocytomas” dominated by high levels of GFAP, which overlaps extensively with tdTOM." (PMID 39609428, 2024). "Olig2 is a marker of oligodendrocyte that is often used to identify astrocytoma and oligodendrocyte tumor." (PMID 36990974, 2023). "Phosphorylation of the serine motif of Olig2 promotes proliferation of neural progenitor cells and induces potential astrocytoma malignancies." (PMID 33833342, 2021). "Highexpression of OLIG1 and OLIG2 is also seen in anaplasticoligodendroglioma and astrocytoma." (PMID 31312081, 2019). "Histopathological features were of a moderately hypercellular astrocytoma (GFAP, Olig2 immunohistochemical staining positive) with mild cytological atypia and focal infiltrative growth (demonstrated with neurofilament NF68 staining)." (PMID 39427038, 2024). "All tumors generated were composed of regions with more oligo- and mixed astrocytoma histologies, with areas that were highly positive for GFAP and others positive for Olig2." (PMID 21931722, 2011). "Both astrocytomas and oligodendroglial tumors in humans demonstrate diffuse expression of OLIG1 and OLIG2, although expression of OLIG2 is lower and increasingly variable and heterogeneous in GBM as compared to ODG tumors." (PMID 16018821, 2005). "Despite the absence of Olig2 labeling, J3TBg tumors were assigned as diffuse gliomas considering their close morphology with J3T tumors (confirmed to be high-grade astrocytomas) and the presence of typical palisading necrotic areas in 2 tumors." (PMID 38098992, 2023). "Importantly, we observed that the tumor cells in the center zone displayed a prominent enrichment of stem cell markers Sox2 and Sox9, but did not express differentiated cell markers Olig2, CC1, S100β, and PDGFRα as observed in oligodendrocytoma and/or astrocytoma." (PMID 33863883, 2021).
ependymoma (19 papers, 2019 to 2025). A WHO grade II, slow growing tumor of children and young adults, usually located intraventricularly. "Additionally, some ependymomas show significant OLIG2 immunostaining, consistent with transdifferentiation into glial-precursor-like cells in a subset of tumor cells." (PMID 41464145, 2025). "However, normal glial cells and glia-like tumor cells have their specific lineage-associated genes, such as FABP7 and MSX1 in normal ASCs, OLIG2 and OPCML in normal OPCs and OLs, FRMD5 in ASC-like ependymomas and GLUL in OPC/OL-like ependymomas." (PMID 37095395, 2023). "However, supratentorial ependymoma is characterized by clear cell morphology, negativity for oligodendrocyte transcription factor 2 (OLIG2), dot-like epithelial membrane antigen (EMA) positivity, and positivity for L1 cell adhesion molecule (L1CAM) and p65/RELA markers." (PMID 39440342, 2024). "Immunohistochemically, ependymomas arising in other locations, are characterized by positivity for GFAP, negativity for OLIG2, and dot-like or ring-like cytoplasmic positivity for EMA." (PMID 38544524, 2024). "Ependymoma (clear cell phenotype) can show EMA and CD99 immunopositivity and scattered oligodendrocyte transcriptional factor-2 (OLIG2) immunopositive cells in the neoplasm." (PMID 35885538, 2022). "Additionally, nuclear immunostaining for Olig2 in tumor cells tends to rule out most cases of ependymoma." (PMID 39953192, 2025). "Moreover, OLIG2 positivity is a useful tool, since ependymoma generally does not express it." (PMID 31114608, 2019). "Immunohistochemistry shows positivity for GFAP, negativity for OLIG2, and absence of dot-like EMA positivity, which instead characterizes other ependymomas." (PMID 38544524, 2024). "The ependymoma-like aspect coupled with the lack of diffuse GFAP immunostaining and the presence of OLIG2 positivity are useful clues for recognizing these tumors in histopathological practice." (PMID 38216991, 2024). "OLIG2 mRNA was absent from cases of the RELA-like and tanycytic ependymomas but expressed in the two astroblastoma-like tumors." (PMID 33481105, 2021). "In EWSR1-PLAGL1 fusion cases the absence of OLIG2 and SOX10 staining with relatively solid growth pattern are ependymal-like features, though ependymoma type EMA staining was only convincingly present in one case with focal/rare paranuclear dot-like staining in two cases." (PMID 39228008, 2024). "Indeed, the cases histopathologically presented as “mixed subependymomas-ependymomas” with well-circumscribed tumors exhibiting a diffuse immunoreactivity for GFAP, without expression of Olig2 or SOX10." (PMID 38581034, 2024).
brain tumor (18 papers, 2012 to 2025). "Here, we hypothesized that the loss of both ASCL1 and OLIG2 should prevent or significantly reduce brain tumor formation and/or progression, resulting in an increase in survival." (PMID 39609428, 2024). "In summary, our comprehensive in vivo analyses of ASCL1 and OLIG2 loss- and gain-of-functions in primary brain tumors provide proof of concept of the combinatorial function of these two bHLH transcription factors in determining the lineage hierarchy, heterogeneity, and plasticity of GBMs." (PMID 39609428, 2024). "OLIG2 is a gene involved in central nervous system development, and there are reports that this gene plays an important role in the maintenance of brain tumors, especially GSCs." (PMID 38418476, 2024). "Here, we show that induction of somatic mutations in subventricular zone (SVZ) progenitor cells leads to the dysregulation of ASCL1 and OLIG2, which then function redundantly and are required for brain tumor formation in a mouse model of GBM." (PMID 39609428, 2024). "The salient features of genes OLIG1, OLIG2 and OLIG3 havingconserved bHLH domain that are associated with brain tumor arediscussed." (PMID 31312081, 2019). "The oligodendroglial marker OLIG2 isuniversally expressed in diffuse glioma and lower in other braintumors." (PMID 31312081, 2019). "Comparative genomics revealed that the zebrafish RB1 brain tumors are most similar to the human OLIG2+/SOX10+ CNS-PNET subtype." (PMID 29914980, 2018). "Together, these results demonstrate the zebrafish rb1 brain tumors have a highly proliferative, poorly differentiated state with an oligoneural precursor molecular signature found in human OLIG2+/SOX10+ and zebrafish NRAS CNS-PNETs." (PMID 29914980, 2018). "We previously found that ectopic expression of ING5 increased the expression of the Oct4, Olig2 and nestin neural stem cell markers in stem-like brain tumour initiating cells (BTICS) in vitro while promoting self-renewal, preventing lineage differentiation, and increasing stem cell pools." (PMID 39787145, 2025). "On serial sections from one individual mouse brain we could see that SOX2 was also co-expressed with OLIG2, which is a surrogate marker for brain tumor cells." (PMID 22931209, 2012). "More importantly, we also validated in the various mouse brain tumor types that genes of this transcriptional network and the cell types (NSC/NPC, astrocyte, OPC) associated with their function were altered accordingly in the absence or elevated levels of ASCL1 and/or OLIG2." (PMID 39609428, 2024). "It was further supported by using lipopolymeric nanoparticle-containing combo siRNA (OLIG2, POU3F2, SALL2, and SOX2) targeting brain tumor-initiating cells (BTICs) in a mouse brain tumor model." (PMID 34944911, 2021). "p53MYC astrocytes additionally expressed CD133, Olig2 and Musashi-1 which are considered to be neural stem cell (NSC) markers observed in undifferentiated brain tumor initiating cells (BTIC)." (PMID 23424671, 2013).
schizophrenia (17 papers, 2007 to 2026). A major psychotic disorder characterized by abnormalities in the perception or expression of reality. "There are consistent reports of reduced expression of genes (MAG, MAL, MBP, PLP, MOG, NRG1, and Olig2, among others) associated with oligodendrocytes and myelin, and therefore involved in neuronal development or signal transmission in schizophrenia." (PMID 35326310, 2022). "We do not find significant differences in the percentages of proteins associated with ID, ASD or schizophrenia between the interactomes of starting transcription factors Tcf4, Olig2, Npas3, Sox2 (P-value >0.2 for all MD categories)." (PMID 28375211, 2017). "Genetic association analysis showed that OLIG2 is associated with schizophrenia and demonstrated an epistatic effect with 2′,3′-cyclic nucleotide 3′-phosphodiesterase (CNP) and ERBB4." (PMID 24478629, 2014). "Interestingly, two szDMPs (FDR < 0.2) in OLIG2+ are located within the regions reported to be associated with schizophrenia by GWAS including a CpG located in the intron of NT5C2 gene, involved in purine metabolism." (PMID 31288836, 2019). "Moreover, OLIG2 deregulation has been associated with disorders such as schizophrenia and Alzheimer's disease." (PMID 21206754, 2010). "A recent study indicated that Olig2 influences susceptibility to schizophrenia." (PMID 18021424, 2007). "As a regulator of Olig2, Olig1 could be considered as another candidate gene for the susceptibility to schizophrenia." (PMID 18021424, 2007). "In postmortem studies, mRNA levels of Olig2 have been found reduced in patients with schizophrenia compared to healthy individuals." (PMID 32425837, 2020). "At a moderately stringent FDR < 0.2, we identify 261 individual CpGs (60 in NeuN+ and 201 in OLIG2+) that are differentially methylated between control and schizophrenia." (PMID 31288836, 2019). "We identified 140 and 167 differentially expressed genes between control and schizophrenia (referred to as “szDEGs” henceforth) for NeuN+ and OLIG2+, respectively, at FDR < 0.01 (see the “Methods” section)." (PMID 31288836, 2019). "Parallel and multistep analysis in this research showed that SLC1A1, DRD2, DRD4, BDNF, ESR1, CDH2, GRIN2B, TNFa, GABBR1, and OLIG2 are common genes between schizophrenia and OCD which ESR1, DRD2, GABBR1, TNFa, and CDH2 are the most important individuals." (PMID 31086558, 2018). "Considering that NeuN+ tend to be more hypermethylated compared to OLIG2+, we investigated whether disease patterns in schizophrenia contribute to reduced cell type difference in DNA methylation." (PMID 31288836, 2019). "We next analyzed whole-genome methylation maps from brain tissue from patients with schizophrenia (28 NeuN+ and 22 OLIG2+) and contrasted these data with data from matched controls (25 NeuN+ and 20 OLIG2+; see the “Methods” section) described in the previous section." (PMID 31288836, 2019). "Furthermore, OLIG2 expression significantly correlated in cerebral cortex with CNP and ERBB4, suggesting that variation in OLIG2 confers susceptibility to schizophrenia as part of a network of genes implicated in oligodendrocyte function." (PMID 24478629, 2014). "Moreover, the symptoms of anxiety are shared by some other psychiatric disorders, like schizophrenia, suggesting that the anxiety like behavior found in Olig2 cKO mice may also contribute to other psychiatric disorders." (PMID 26696827, 2015). "Genetic and neuroimaging data have shown that the MAG, Olig2, and CNP genes can influence white matter integrity and cognitive performance in schizophrenia patients." (PMID 32425837, 2020).